MIR4285 (microRNA 4285)
Synonyms: hsa-mir-4285
Gene: MicroRNA gene on chromosome 7 (102,293,103 to 102,293,187, forward strand). Ensembl gene ENSG00000264675.
Diseases named in the same sentence as MIR4285 in open-access papers:
MIR4285 is named in the same sentence as 1 disease in open-access papers, as found by Europe PMC text mining. Sharing a sentence is not in itself a finding about the gene and the disease.
MIR4285 shares sentences with these, for which no sentence is quoted: cancer (1 paper).